AK9 (adenylate kinase 9)
Description:
Broad-specificity nucleoside phosphate kinase involved in cellular nucleotide homeostasis by catalyzing nucleoside-phosphate interconversions. Similar to other adenylate kinases, preferentially catalyzes the phosphorylation of the nucleoside monophosphate AMP with ATP as phosphate donor to produce ADP. In vitro, can also catalyze the phosphorylation of CMP, dAMP and dCMP and use GTP as an alternate phosphate donor. Moreover, exhibits a diphosphate kinase activity, producing ATP, CTP, GTP, UTP, TTP, dATP, dCTP and dGTP from the corresponding diphosphate substrates with either ATP or GTP as phosphate donors. For this activity shows the following substrate preference CDP > UDP > ADP > TDP.
Synonyms: AKD1; AKD2; C6orf199; C6orf224; FLJ42177; FLJ25791; dJ70A9.1; MGC26954; AK 9; SPGF89
Tractability: PROTAC: ubiquitination databases record sites on it.
Gene: Protein-coding gene on chromosome 6 (109,492,855 to 109,691,217, reverse strand). Ensembl gene ENSG00000155085.
Subcellular location: Cytoplasm; Nucleus; Cell projection, cilium, flagellum
Subcellular location (Human Protein Atlas): Nuclear membrane; Nucleoplasm; Calyx; Cytosol
Pathways (Reactome):
Metabolism: Interconversion of nucleotide di- and triphosphates
Gene Ontology:
Molecular function: AMP kinase activity; CMP kinase activity; dAMP kinase activity; dCMP kinase activity; nucleoside diphosphate kinase activity; nucleoside monophosphate kinase activity; ATP binding; nucleobase-containing compound kinase activity; nucleoside triphosphate adenylate kinase activity; phosphotransferase activity, phosphate group as acceptor
Biological process: CDP biosynthetic process; UDP biosynthetic process
Cellular component: cytoplasm; cytosol; nuclear membrane; nucleoplasm; nucleus; motile cilium
Genetic constraint (gnomAD): Loss-of-function variants: 151 observed, 203.84 expected, observed/expected ratio (o/e) 0.74, 90% interval 0.65 to 0.85. The upper end of that interval is the gene's LOEUF score, 0.85, which puts it in group 3 of 6, group 1 being the genes least tolerant of losing a copy. Missense variants: 1,781 observed, 2,065.2 expected, observed/expected ratio (o/e) 0.86, 90% interval 0.83 to 0.9. Synonymous variants: 623 observed, 678.52 expected, observed/expected ratio (o/e) 0.92, 90% interval 0.86 to 0.98.
Homologues: Orthologues: chimpanzee AK9 (99% identical), macaque AK9 (96% identical), mouse Ak9 (71% identical), rat Ak9 (71% identical), zebrafish ak9 (40% identical), Caenorhabditis elegans F13E6.2 (4% identical), Drosophila melanogaster CG9541 (3% identical). Paralogues in human: AK8 (6% identical), AK7 (5% identical), AK5 (4% identical), AK4 (3% identical), AK4P3 (3% identical), AK2 (2% identical), AK3 (2% identical), AK1 (2% identical), CMPK1 (2% identical).
Diseases named in the same sentence as AK9 in open-access papers:
AK9 is named in the same sentence as 8 diseases in open-access papers, as found by Europe PMC text mining. Sharing a sentence is not in itself a finding about the gene and the disease. The quoted sentences say what the papers report.
male infertility (2 papers, 2023 to 2025). The inability of the male to effect fertilization of an ovum after a specified period of unprotected intercourse. "Here, we show that Ak9 regulates the motility of sperm and motile cilia in mammals and that AK9 mutations can cause male infertility and communicating hydrocephalus." (PMID 38100419, 2023). "Interestingly, in humans, mutation in AK9 also causes male infertility, while mutations in AK7, besides male infertility, were correlated with PCD and caused PCD in mice." (PMID 40886204, 2025).
age (1 paper, 2023). A temporal measurement of the time period elapsed since an identifiable point in the life cycle of an organism. "Mice that are heterozygous for iNPH-associated CWH43 or AK9 mutations develop an iNPH-like syndrome that is characterized by grossly normal appearance and behavior, normal lifespan, age-dependent communicating hydrocephalus, and impairments of gait or balance." (PMID 38100419, 2023).
communicating hydrocephalus (1 paper, 2023). An abnormal accumulation of cerebrospinal fluid within the ventricles of the brain that occurs as a consequence of impaired cerebrospinal fluid reabsorption by the arachnoid granulations. "Our studies in mice harboring heterozygous iNPH-associated mutations in either CWH43 or AK9 show that these mutations can cause communicating hydrocephalus in an autosomal dominant manner." (PMID 38100419, 2023).
congenital myasthenia (1 paper, 2023). "Another report suggested that intronic mutations in AK9 may act as a disease modifier in combination with RAPSN mutations in limb-girdle congenital myasthenia, but causality or a mechanism of action was not determined." (PMID 38100419, 2023).
Hydrocephalus (1 paper, 2023). Hydrocephalus is an active distension of the ventricular system of the brain resulting from inadequate passage of CSF from its point of production within the cerebral ventricles to its point of absorption into the systemic circulation. "Genetically engineered mice that are heterozygous for an iNPH-associated damaging mutation in AK9 (which encodes adenylate kinase 9) appear normal and are fertile at birth, but develop communicating hydrocephalus and imbalance as they age." (PMID 38100419, 2023). "Mutations in AK9 were previously identified in a mutagenic screen for genes that cause hydrocephalus in zebrafish." (PMID 38100419, 2023). "Mice homozygous for an iNPH-associated AK9 mutation displayed normal cilia structure and number, but decreased cilia motility and beat frequency, communicating hydrocephalus, and balance impairment." (PMID 38100419, 2023). "Mice harboring AK9 mutations displayed decreased cilia beat frequency, communicating hydrocephalus, and balance impairment." (PMID 38100419, 2023). "AK9+/− mice displayed normal brain development and behavior until early adulthood, but subsequently developed communicating hydrocephalus." (PMID 38100419, 2023). "AK9+/− mice displayed normal brain development and behavior until early adulthood, but subsequently developed hydrocephalus." (PMID 38100419, 2023). "We find that iNPH-associated mutations affecting two of these genes, AK9 and CWH43, alter ependymal motile cilia function and cause an iNPH-like syndrome in mice that is characterized by communicating hydrocephalus and balance impairment." (PMID 38100419, 2023). "AK9−/− mice (four females and one male), displayed very large ventricles at 3 mo, while AK9+/− mice (seven males) had no signs of hydrocephalus at P7 or at 3 mo." (PMID 38100419, 2023).
tumor (1 paper, 2021). "Three of the nine isoforms demonstrated significant changes between tumor stages (ANOVA, p* <0.05), with AK4/7 expression appearing to increase and AK9 expression to decrease with tumor stage." (PMID 34940617, 2021).
AK9 also shares sentences with these, for which no sentence is quoted: lung adenocarcinoma (1 paper); X-linked disease (1).